ASPH (aspartate beta-hydroxylase)
Description:
[Isoform 1]: Specifically hydroxylates an Asp or Asn residue in certain epidermal growth factor-like (EGF) domains of a number of proteins. [Isoform 8]: Membrane-bound Ca(2+)-sensing protein, which is a structural component of the ER-plasma membrane junctions. Isoform 8 regulates the activity of Ca(+2) released-activated Ca(+2) (CRAC) channels in T-cells.
Synonyms: BAH; CASQ2BP1; JCTN; HAAH; AAH; FDLAB; junctin
Tractability: Small molecule: a structure with a bound ligand is known; a high-quality ligand is known. Antibody: its Gene Ontology location is reachable by antibodies, with high confidence; UniProt predicts a signal peptide or a membrane-spanning region. PROTAC: ubiquitination databases record sites on it; its protein half-life has been measured; a small molecule that binds it is known.
Target class: Enzyme; Oxidoreductase
Gene: Protein-coding gene on chromosome 8 (61,500,549 to 61,714,768, reverse strand). Ensembl gene ENSG00000198363.
Subcellular location: Endoplasmic reticulum membrane (Isoform 1); Sarcoplasmic reticulum membrane (Isoform 4); Endoplasmic reticulum membrane (Isoform 8)
Subcellular location (Human Protein Atlas): Endoplasmic reticulum
Pathways (Reactome):
Metabolism of proteins: Protein hydroxylation
Muscle contraction: Ion homeostasis
Transport of small molecules: Stimuli-sensing channels
Gene Ontology:
Molecular function: peptidyl-aspartic acid 3-dioxygenase activity; protein binding; calcium ion binding; electron transfer activity; structural constituent of muscle; structural molecule activity
Biological process: positive regulation of proteolysis; muscle contraction; regulation of cytosolic calcium ion concentration; regulation of protein depolymerization; regulation of protein stability
Cellular component: cortical endoplasmic reticulum; endoplasmic reticulum; plasma membrane; endoplasmic reticulum membrane; cytoplasm; membrane; sarcoplasmic reticulum membrane
Genetic constraint (gnomAD): Loss-of-function variants: 74 observed, 88.79 expected, observed/expected ratio (o/e) 0.83, 90% interval 0.69 to 1.01. The upper end of that interval is the gene's LOEUF score, 1.01, which puts it in group 4 of 6, group 1 being the genes least tolerant of losing a copy. Missense variants: 753 observed, 746.47 expected, observed/expected ratio (o/e) 1.01, 90% interval 0.95 to 1.07. Synonymous variants: 260 observed, 270.74 expected, observed/expected ratio (o/e) 0.96, 90% interval 0.87 to 1.06.
Homologues: Orthologues: chimpanzee ASPH (99% identical), macaque ASPH (93% identical), pig ASPH (84% identical), rat Asph (82% identical), mouse Asph (82% identical), dog ASPH (81% identical), guinea pig ASPH (73% identical), tropical clawed frog asph (64% identical), zebrafish unm_hu7910 (51% identical), Drosophila melanogaster Asph (36% identical), Caenorhabditis elegans K09A9.6 (26% identical). Paralogues in human: ASPHD1 (11% identical), ASPHD2 (11% identical).
Diseases named in the same sentence as ASPH in open-access papers:
ASPH is named in the same sentence as 90 diseases in open-access papers, as found by Europe PMC text mining. Sharing a sentence is not in itself a finding about the gene and the disease. The quoted sentences say what the papers report.
hepatocellular carcinoma (24 papers, 2006 to 2026). A malignant tumor that arises from hepatocytes. "For instance, ASPH overexpression in hepatocellular carcinoma (HCC) correlates significantly with tumor aggressiveness and metastasis." (PMID 41212437, 2025). "ASPH-mediated upregulation of Notch1 signaling by hydroxylation of Notch1 and its ligands has been detected in various cancer types, such as hepatocellular carcinoma (HCC) 8, pancreatic cancer 10, and breast cancer." (PMID 38817852, 2024). "Notch modulation by ASPH has been well characterized in neuroblastoma 31, hepatocellular carcinoma 32, and prostate 21, pancreatic 10, and breast cancers." (PMID 38817852, 2024). "Among them, INPP5F has been recently demonstrated to be an oncogene that activates the ASPH-mediated Notch-c-MYC/cyclin E1 pathway in hepatocellular carcinoma." (PMID 37469520, 2023). "ASPH overexpression—in the case of hepatocellular carcinoma (HCC), for example—produces a malignant phenotype characterized by increased cell motility, invasion and metastases." (PMID 36293298, 2022). "In the study of hepatocellular carcinoma, the antigenicity of ASPH can be used to load ASPH on dendritic cells to induce the production of CD4+ T cells, and the antitumor effect can be achieved through this immune response." (PMID 35965520, 2022). "ASPH is reported as a malignant factor in hepatocellular carcinoma, glioma, and pancreatic cancer, and its targeting reduces proliferation and invasion of prostate cancer cells through Notch signalling modulation." (PMID 33846420, 2021). "MiR-200a restrained the proliferation and motility of hepatocellular carcinoma cells through reducing ASPH level." (PMID 33526034, 2021). "Different cancers have different ASPH expression patterns, and while surface expression is quite common in pancreatic cancer and hepatocellular carcinoma, intracellular overexpression patterns have also been observed." (PMID 32811566, 2020). "Next, a suppressant role of the microRNA miR-200a in posttranscription regulation of the ASPH expression in hepatoma cells has been found." (PMID 32811566, 2020). "Finally, as far as we know, there have been a few studies focusing on ASPH and cancers, such as pancreatic ductal adenocarcinoma, hepatocellular carcinoma, and cholangiocarcinoma, but this is the first report on the relationship between ASPHD1 and melanoma." (PMID 37004045, 2023). "In another study on the recombinant bacteriophage Lambda, antitumor immunity in hepatocellular carcinoma was induced by Lambda phages expressing human ASPH (aspartate β-hydroxylase)-derived proteins on their GpD proteins (approximately 405 to 420 copies are present per phage particle)." (PMID 37112745, 2023). "ASPH is known to be involved in the cellular senescence in hepatocellular carcinoma and gliomas." (PMID 33015050, 2020). "Gsk3β has been reported to be regulated by ASPH inhibitor in hepatocellular carcinoma." (PMID 33015050, 2020). "Human ASPH was originally cloned by the immunoscreening of cDNA libraries prepared from human osteosarcoma and hepatocellular carcinoma (HCC) cell lines." (PMID 40149287, 2025). "ASPH overexpression may promote tumor cell formation, proliferation, invasion, and metastasis, becoming an indicator of malignant expression and considered a potential tumor marker, which is currently more studied in hepatocellular carcinoma." (PMID 35965520, 2022). "Furthermore, a recent study identified mitochondrial localization of ASPH in hepatocellular carcinoma (HCC)." (PMID 32811566, 2020). "ASPH protein is overexpressed in a variety of malignancies, such as non-small cell lung cancer (NSCLC), pancreatic cancer, cholangiocarcinoma, hepatocellular carcinoma (HCC) and colorectal cancer." (PMID 31694640, 2019). "Importantly, in hepatocellular carcinoma (HCC), Notch signaling can be activated directly by ASPH upregulation to promote tumor cell migration, invasion and metastases." (PMID 26954680, 2016).
hepatocellular carcinoma (continued). "Elevated expression of ASPH has been observed in multiple malignancies, including non-small cell lung cancer, where its levels are significantly increased in bronchoalveolar lavage exosomes, as well as in pancreatic cancer, colorectal cancer, breast cancer, and hepatocellular carcinoma." (PMID 41312363, 2025).
breast carcinoma (11 papers, 2019 to 2025). "This study aims to explore molecular mechanisms underlying how ASPH network regulates designated exosomes to program development and progression of breast cancer." (PMID 31694640, 2019). "Therefore, ASPH is proposed to be a potential diagnostic and prognostic marker for breast cancer." (PMID 31694640, 2019). "For instance, ASPH promoted the interaction between Notch and JAG to keep Notch receptors, ligands, and regulators stable and strengthened ligand-receptor binding, which confirmed that ASPH-Notch axis was critical in carcinogenesis in breast cancer." (PMID 38702698, 2024). "Similar effects of ASPH on cancer cells through activating Notch cascade are displayed in breast cancer." (PMID 36982561, 2023). "This inhibition was rescued by re-addition of purified exosomes released from breast cancer cells with exogenous ASPH." (PMID 31694640, 2019). "The purpose of this study is to evaluate potential value of aspartate β-hydroxylase (ASPH) as a therapeutic target for breast cancer metastasis." (PMID 31694640, 2019). "ASPH is proposed to guide breast cancer cells to synthesize, release/secrete and deliver metalloproteinases enriched exosomes." (PMID 31694640, 2019). "Expression profile of ASPH-Notch axis was demonstrated in a panel of human breast cancer cell lines." (PMID 31694640, 2019). "Expression profiling of Notch signaling components positively correlates with ASPH expression in breast cancer patients, confirming that ASPH-Notch axis acts functionally in breast tumorigenesis." (PMID 31694640, 2019). "ASPH’s pro-oncogenic/pro-metastatic properties are essential for breast cancer development/progression, revealing a potential target for therapy." (PMID 31694640, 2019). "ASPH instructs the more malignant breast cancer cells (donors) to synthesize/secrete exosomes delivering designated elements, aiming to reprogram fundamental processes of the less malignant cells (recipients), such as cytoskeleton dynamics, metabolism, stemness and multifaceted metastasis." (PMID 31694640, 2019). "We examined ASPH expression profiling in several human breast cancer cell lines." (PMID 31694640, 2019). "We hypothesized MMPs (ADAMs) as executive effectors of exosomes are pivotal for ASPH mediated aggressive phenotypes of breast cancer cells." (PMID 31694640, 2019). "Collectively, to the best of our knowledge, for the first time, this study has revealed a fundamental role of ASPH in propagating invasion, aggressiveness and multi-organ dissemination, thus establishing ASPH as a potential therapeutic target for multifaceted metastasis of breast cancer." (PMID 31694640, 2019). "We proposed, through activating Notch cascade, ASPH could instruct breast cancer cells to synthesize/release designated exosomes, leading to dissemination and metastatic outgrowth." (PMID 31694640, 2019). "Breast cancer cells highly expressing ASPH accelerated tumor development and progression." (PMID 31694640, 2019). "Furthermore, the ASPH-notch Axis could intricately orchestrate the exosomal transport of prometastatic secretome, thereby facilitating multi-organ metastasis in breast cancer." (PMID 38702698, 2024). "In addition, the inhibition of ASPH suppresses the migration of ASPH-overexpressing MDA-MB-231 cells in vitro, suggesting that ASPH might be a potential target for the treatment of brain metastasis in HER2-positive breast cancer as well." (PMID 32640677, 2020). "However, it is yet to be illustrated whether Notch cascade activated by ASPH is a major molecular mechanism to generate and maintain malignant cellular behaviors in breast cancer." (PMID 31694640, 2019). "Indeed, ASPH activates Notch signaling in breast cancer patients." (PMID 31694640, 2019). "Activation of the ASPH-SRC axis is a key driver of tumor progression in pancreatic 15 and breast cancer." (PMID 38817852, 2024).
breast carcinoma (continued). "Transmembrane 4 L-six family member 1 (TM4SF1) and aspartate beta-hydroxylase (ASPH), both reported as multiorgan metastasis-promoting genes in breast cancer, were included in these signature genes." (PMID 32640677, 2020). "MMPs/ADAMs act as outlets of ASPH-Notch axis-activation and immediate effectors for ECM degradation/remodeling to initiate multistep metastasis of breast cancer cells." (PMID 31694640, 2019). "Moderate-high expression of ASPH confers more aggressive molecular subtypes (TNBC or Her2 amplified), early recurrence/progression and devastating outcome (reduced overall/disease-free survival) of breast cancer." (PMID 31694640, 2019). "ASPH is detectable in 90.1% of breast cancer patients, but not in inflammatory disease or benign tumor." (PMID 31694640, 2019). "ASPH was detected in 90.1% of breast cancer patients, with a negative, low, moderate or high expression rate of 9.9, 6.4, 43.3, and 41.1%, respectively." (PMID 31694640, 2019). "Notably, Notch pathway elements were consistently downregulated or upregulated in ASPH negative vs. positive breast cancer patients." (PMID 31694640, 2019).
cholangiocarcinoma (11 papers, 2008 to 2025). A carcinoma that arises from the intrahepatic biliary tree (intrahepatic cholangiocarcinoma) or from the junction, or adjacent to the junction, of the right and left hepatic ducts (hilar cholangiocarcinoma). "The overexpression of ASPH in several human solid tumors, such as pancreatic ductal adenocarcinoma, breast cancer, colorectal cancer, cholangiocarcinoma, and hepatocarcinoma, has been observed." (PMID 37004045, 2023). "One gene related to cardiac conduction, ASPH, is highly overexpressed in cholangiocarcinoma(CCA) and HCC." (PMID 33819263, 2021). "It has been reported that ASPH high expression is associated with poor survival of HCC and cholangiocarcinoma patients." (PMID 25483102, 2015). "In cholangiocarcinoma, ASPH may promote cholangiocarcinoma progression by regulating RB1 phosphorylation." (PMID 35965520, 2022). "Such combination therapy may have wide application to various solid tumors, such as liver, pancreas, gastric, esophageal, breast, cholangiocarcinoma and sarcomas since these tumors highly express ASPH." (PMID 35392977, 2022). "It was worth mentioning that ASPH expression was relatively low or negligible in normal adult tissues but very high in a number of malignancies, including HCC, cholangiocarcinoma, lung, breast, and colon cancer, plus the neoplasms of the nervous system." (PMID 38702698, 2024). "Previous studies have established that ASPH is a target for immunotherapy using a dendritic cell (DC) vaccine approach in syngeneic animal models of HCC and cholangiocarcinoma." (PMID 35392977, 2022).
pancreatic cancer (9 papers, 2019 to 2025). "Dong also found that ASPH is highly overexpressed in pancreatic cancer (PC) and ASPH upregulation confers a malignant phenotype characterized by enhanced cell proliferation, migration, invasion and colony formation in vitro as well as PC tumor growth in vivo." (PMID 40110547, 2025). "A study using a first-generation ASPH inhibitor (MO-I-1100) reported findings consistent with our results, linking growth reduction in pancreatic cancer to downregulation of the Notch signaling pathway." (PMID 38817852, 2024). "This study together with previous findings establishes ASPH as a therapeutic target for pancreatic cancer." (PMID 31888763, 2019). "In addition, Elevated levels of ASPH expression can also facilitate the advancement of cholangiocarcinoma and pancreatic cancer, ultimately resulting in adverse clinical outcomes." (PMID 40110547, 2025). "Besides, ASPH was also overexpressed in pancreatic cancer and played an active part in the regulation of pancreatic cancer cells’ proliferation, migration, and invasion by a variety of signaling pathways." (PMID 38702698, 2024). "We explored if dysregulated ASPH is critically involved in pancreatic cancer pathogenesis." (PMID 31888763, 2019). "Therefore, the ASPH-SRC axis-mediated pro-invasive invadopodia are collapsed following treatment and ASPH’s pro-metastatic properties are diminished in pancreatic cancer." (PMID 31888763, 2019). "We hypothesized ASPH acts as an activator of SRC signaling to promote tumor progression in pancreatic cancer." (PMID 31888763, 2019). "Importantly, we have demonstrated a paramount role of the ASPH-SRC axis in determining clinical outcome of patients with pancreatic cancer." (PMID 31888763, 2019). "ASPH promotes pancreatic cancer progression through activating the SRC signaling pathway." (PMID 31888763, 2019). "However, how ASPH regulates downstream effectors as a determinate for aggressive/invasive phenotypes of pancreatic cancer cells remains mysterious." (PMID 31888763, 2019). "Therefore, ASPH is promising to serve as a biomarker for early diagnostics and prognostics of pancreatic cancer." (PMID 31888763, 2019). "Expression profile of ASPH in human pancreatic cancer cell lines has been evaluated previously." (PMID 31888763, 2019). "Thus, we hypothesized the ASPH-SRC axis integrates invadopodia machinery to drive metastasis of pancreatic cancer cells." (PMID 31888763, 2019). "However, whether invadopodia play a role in ASPH-induced aggressive malignant phenotypes of pancreatic cancer has yet to be disclosed." (PMID 31888763, 2019). "ASPH activates SRC cascade in the primary PDAC tumor, upregulates downstream target genes (e.g., MMPs), and contributes to multiple steps of pancreatic cancer metastasis." (PMID 31888763, 2019). "Collectively, ASPH activated the SRC signaling pathway to generate and maintain malignant phenotypes in pancreatic cancer." (PMID 31888763, 2019). "Compared to a negative-low level, a moderate-very high level of ASPH, ADAM12, activated SRC, and MMPs correlated with curtailed overall survival (OS) of pancreatic cancer patients (log-rank test, ps < 0.001)." (PMID 31888763, 2019).
glioma (8 papers, 2018 to 2024). A benign or malignant brain and spinal cord tumor that arises from glial cells (astrocytes, oligodendrocytes, ependymal cells). "While higher expression of ASPH has been reported in some cancer stem cells such as glioma stem cells, its expression on leukemia stem cells (LSC) is not well described." (PMID 35004304, 2021). "Recently ASPH was suggested as a potential biomarker in gliomas." (PMID 33265245, 2018). "The upregulation of circ-ASPH regulated AR expression in Glioma by targeting the miR-599/AR/SOCS2-AS1 signaling pathway, thus promoting glioma development." (PMID 39256355, 2024).